C1QL4 (complement C1q like 4)
Description:
May regulate the number of excitatory synapses that are formed on hippocampus neurons. Has no effect on inhibitory synapses (By similarity). May inhibit adipocyte differentiation at an early stage of the process (By similarity).
Synonyms: CTRP11; C1QTNF11
Tractability: Antibody: UniProt places it where antibodies can reach, with medium confidence; UniProt predicts a signal peptide or a membrane-spanning region; its Gene Ontology location is reachable by antibodies, with medium confidence. PROTAC: ubiquitination databases record sites on it.
Gene: Protein-coding gene on chromosome 12 (49,332,409 to 49,337,188, reverse strand). Ensembl gene ENSG00000186897.
Subcellular location: Secreted
Subcellular location (Human Protein Atlas): Vesicles; Cytosol; Predicted to be secreted
Gene Ontology:
Molecular function: protein binding; identical protein binding
Biological process: maintenance of synapse structure; trans-synaptic signaling, modulating synaptic transmission
Cellular component: synapse; synaptic cleft; extracellular region
Genetic constraint (gnomAD): Loss-of-function variants: 5 observed, 11.77 expected, observed/expected ratio (o/e) 0.42, 90% interval 0.22 to 0.89. The upper end of that interval is the gene's LOEUF score, 0.89, which puts it in group 3 of 6, group 1 being the genes least tolerant of losing a copy. Missense variants: 367 observed, 324.45 expected, observed/expected ratio (o/e) 1.13, 90% interval 1.04 to 1.23. Synonymous variants: 168 observed, 137.99 expected, observed/expected ratio (o/e) 1.22, 90% interval 1.07 to 1.38.
Homologues: Orthologues: chimpanzee C1QL4 (100% identical), dog C1QL4 (99% identical), guinea pig C1QL4 (99% identical), pig C1QL4 (99% identical), rabbit C1QL4 (98% identical), mouse C1ql4 (97% identical), rat C1ql4 (97% identical), macaque C1QL4 (95% identical), tropical clawed frog c1ql4 (79% identical), zebrafish c1ql4b (75% identical), zebrafish c1ql4a (73% identical). Paralogues in human: C1QL1 (73% identical), C1QL3 (71% identical), C1QL2 (67% identical), COL8A2 (33% identical), COL10A1 (32% identical), C1QTNF2 (32% identical), C1QB (32% identical), C1QTNF5 (31% identical), COL8A1 (31% identical), C1QTNF7 (31% identical), C1QTNF9 (30% identical), C1QTNF9B (30% identical), and 11 more.
Diseases named in the same sentence as C1QL4 in open-access papers:
C1QL4 is named in the same sentence as 5 diseases in open-access papers, as found by Europe PMC text mining. Sharing a sentence is not in itself a finding about the gene and the disease. The quoted sentences say what the papers report.
breast carcinoma (1 paper, 2023). "To determine the expression status of the C1ql4 gene in breast cancer stem cells, we isolated CD44+CD24- cell populations from MCF-7 cell lines by flow cytometry." (PMID 37324011, 2023). "The effect of C1ql4 on breast cancer progression in vivo was examined in a nude mouse tumor bearing model." (PMID 37324011, 2023).
coronary artery disease (1 paper, 2021). "Differential methylation in the intronic region of the C1QL4 gene has been found in a EWAS of coronary artery disease patients." (PMID 34427971, 2021).
cancer (1 paper, 2023). A tumor composed of atypical neoplastic, often pleomorphic cells that invade other tissues. "Next, we detected whether activation of PI3K/AKT pathway was able to antagonize the inhibitory effects of C1ql4 knockdown on cancer stemness." (PMID 37324011, 2023). "The expression of C1ql4 was significantly higher in BC tissues, compared to para-carcinoma tissues." (PMID 37324011, 2023).
tumor (1 paper, 2023). "Importantly, high C1ql4 expression was obviously associated with tumor size, lymph node metastasis, TNM stage, PR expression status and molecular typing, but not with age, tumor differentiation, HER-2 expression status, ER expression status and Ki-67 expression status." (PMID 37324011, 2023).
C1QL4 also shares sentences with these, for which no sentence is quoted: glioma (1 paper).